IL10 (interleukin 10)
Diseases named in the same sentence as IL10 in open-access papers (continued):
Sharing a sentence is not in itself a finding about the gene and the disease.
malaria (continued). "Overall, our findings suggest that the compositions of EBNA1 and PfSEA-1A-specific IFN-γ expressing T cell memory subsets were influenced by intensity of malaria exposure, whereas T cell subsets expressing IL-10 were dependent on an eBL diagnosis or age." (PMID 34771539, 2021). "After using one-way ANOVA and Dunnett’s Multiple Posthoc to determine difference between control and the three groups, serum IL-10 and IL-6 concentrations significantly elevated with increase in malaria density (p<0.0001)." (PMID 35223394, 2021). "Whole blood IFN-γ and IL-10 production in response to Salmonella was also lower in asymptomatic malaria." (PMID 34177883, 2021). "In vivo, vascular thrombi containing adherent leukocytes were observed in IL-10 knockout (IL-10 KO) mice that had been infected with the rodent malaria parasite P. chabaudi." (PMID 34692564, 2021). "Several previous studies have shown elevated levels of type 2 anti-inflammatory cytokines IL-10 and IL-4 in the malaria-infected group." (PMID 33422078, 2021). "Except for IL-10 secretion, in vitro DC responses to the parasite in malaria-exposed uninfected Malians seem, at least qualitatively, comparable to malaria-naïve US DCs." (PMID 33407502, 2021). "Our study revealed serum IL-10 and IL-6 concentrations significantly elevated with increased in malaria density (p<0.0001)." (PMID 35223394, 2021). "In the context of experimental rodent malaria, IL‐27 (acting via the IL‐27 receptor) was shown to induce the generation of IL‐10‐expressing CD4+ T cells that were critical to limit immunopathology." (PMID 33282291, 2020). "Of note, the contrast between IFN-γ and IL-10 levels has also been correlated with worse clinical presentations in other diseases such as tuberculosis and malaria." (PMID 32784775, 2020). "We observed an inverse relationship between the serum levels of IFN-γ and IL-10 in patients with a first malaria episode compared to those of subjects with previous history of malaria." (PMID 32256470, 2020). "Levels of circulating pro- (IL-6, TNF-α and IFN- Υ) and anti-inflammatory cytokines (IL-10) were highest in clinical malaria." (PMID 33253198, 2020). "Contrarily, IL-10, a Th2 type cytokine, is known to be able to modulate the immune response to malaria parasites and to be involved in deterioration of parasitemia in Plasmodium infection." (PMID 32411650, 2020). "IL-10 levels dropped from baseline values in both donor groups, and the levels stayed significantly higher in malaria-infected donor blood until day 21 when IL-10 levels dropped below the levels in nonmalaria-infected blood." (PMID 33195706, 2020). "In contrast, TGF-β and IL-10 have been identified as important anti–inflammatory immunomodulators that help to limit inflammation and pathology during malaria." (PMID 32043415, 2020). "Increased levels of IL-10 have already been seen in patients with higher parasitaemia and patients with recurrent malaria." (PMID 32696915, 2020). "In our experimental conditions, the presence of BAFF-var primarily altered the levels of two key cytokines implicated in the malaria response, IL8 (pro-inflammatory) and IL10 (anti-inflammatory), especially following exposure to Plasmodium antigens." (PMID 33123155, 2020). "Studies from mice infected with malaria, IL-10 dampen the inflammatory response, prevent tissue damage, and protect animals." (PMID 32599864, 2020). "The levels of anti-inflammatory cytokines, IL-4 and IL-10 in children with microscopic asymptomatic malaria, submicroscopic asymptomatic malaria and uninfected controls were compared." (PMID 33281757, 2020). "Prior reports on NTS infections during malaria, demonstrated that infection-induced IL-10 production and infection-induced hemolysis, and activation of HO-1, were central to impaired immunity to NTS." (PMID 32714882, 2020). "The IL-6/IL-10 ratio, indicating pro/anti-inflammatory balance, was significantly lower in asymptomatic children, compared to clinical malaria." (PMID 33253198, 2020).
malaria (continued). "IL-10 is a potent anti-inflammatory cytokine that can ameliorate malaria pathology and promote secretion of antibodies that can protect against malaria reinfection." (PMID 32450885, 2020). "We determined the levels of pro- and anti-inflammatory mediators as well as that of the regulatory cytokine IL-10 in children with microscopic or submicroscopic asymptomatic malaria and compared to levels in uninfected controls." (PMID 33281757, 2020). "In mouse models of malaria, IL‐27 is an important regulator of IL‐10 producing Type 1 regulatory T (Tr1) cells (Kumar, Ng, & Engwerda, 2019)." (PMID 31890299, 2019). "Some P. falciparum-specific cytokine responses have been associated with protection against clinical malaria, including interferon gamma (IFN-γ), interleukin-10 (IL-10) and tumour necrosis factor (TNF)." (PMID 31806027, 2019). "Another recent study in a malaria endemic area found a subset of γδ T cells from uncomplicated malaria patients expressing Vδ9 T cell receptor that expanded and produced IFNγ and IL-10 when cultured in presence of P. falciparum antigen." (PMID 30809232, 2019). "IL-10 has emerged as an important regulatory molecule in malaria that protects tissues by preventing excessive inflammation." (PMID 30809232, 2019). "In a prospective longitudinal study conducted in a malaria endemic area, IL10 gene polymorphisms associated with high IL-10 production were found to increase the risk of developing clinical malaria in young children." (PMID 30809232, 2019). "In the current study, IL-6 and IL-10 levels were significantly elevated in HAT similar to co-infected cases over malaria mono-infection." (PMID 31687034, 2019). "In this review, we will summarize our current knowledge about IL-10 production during malaria and discuss its impact on disease outcome." (PMID 30809232, 2019). "Treatment of PBMCs from healthy, malaria-free donors with sHz induced increases in IL-12p40 and IL-10 transcripts at 24 h of exposure with further stabilization of the expression levels of the cytokines relative to control conditions." (PMID 31750318, 2019). "The HAT cases expressed significantly higher plasma IFN-γ, IL-6 and IL-10 levels than malaria cases in this study." (PMID 31687034, 2019). "Children who have experienced repeated malaria episodes have a modified immune system that is for instance characterized by an increased production of immunoregulatory cytokine IL-10 and activation of neutrophils, B cells and CD8+ T cells." (PMID 31681289, 2019). "In contrast to IFN-γ, type I IFNs were found to suppress innate and adaptive responses in controlled human malaria studies, inducing the anti-inflammatory cytokine IL-10 and limiting IFN-γ release." (PMID 30972055, 2019). "These cells are prevalent in children living in endemic areas, and the IL-10 they produce has been shown to inhibit malaria-specific pro-inflammatory cytokine production." (PMID 30862316, 2019). "Inflammatory cytokines such as IL-1, IL-6, and IL-10 have been documented in malaria induced thrombocytopaenia." (PMID 31110658, 2019). "Women with Malaria and CHB had similar levels of the liver biomarkers and cytokines, except for significantly higher levels of IL-10 in the Malaria group." (PMID 31002731, 2019). "Results from both pre-clinical malaria models and human studies show that IL-10 not only protects against severe disease, but also inhibits protective anti-parasitic immunity." (PMID 30809232, 2019). "Few reports have also observed a higher IL-12 as well as IL-10 levels following malaria parasitic load." (PMID 31614626, 2019). "Given the many similar mechanisms of T cell IL-10 generation between these two infectious diseases and malaria, it will be important to establish the role of this transcription factor in IL-10 production during Plasmodium infections." (PMID 30809232, 2019).
malaria (continued). "Many studies from malaria endemic countries demonstrated an association of a high TNF-α and IL-10 plasma ratios in young children presenting with SMA44,46,75, which was also a distinguishing factor between our models of severe and moderate anaemia." (PMID 31831787, 2019). "In this review, we will discuss the role of IL-10 during the blood stage of experimental and human malaria, as well as describe the cellular sources of IL-10 and how the production of this potent anti-inflammatory cytokine is regulated." (PMID 30809232, 2019). "Cases with HAT and/or malaria parasites responded with an overall increased secretion of anti-inflammatory cytokines (IL-6, IL-10 and TGF-β)." (PMID 31687034, 2019). "Co-infection led to synergistic stimulation of pro-inflammatory (IFN-γ, TNF-α), and anti-inflammatory (IL-6, and IL-10) cytokine responses relative to malaria mono-infection." (PMID 31687034, 2019). "IL-10 produced by other immune cells during malaria can also influence disease outcome, but the full impact of this IL-10 production is still unclear." (PMID 30809232, 2019). "In particular, elevated levels of IL-10 among the Malaria group is a common finding amongst African multigravidae mothers with P. falciparum infection, and as such, the cytokine has been implicated in the immunopathology of placental malaria." (PMID 31002731, 2019). "IL-10 suppressed IL-12 production by monocytes, which was required for the development of protective immunity against malaria and skewing the cytokine production pattern toward a pro-inflammatory response." (PMID 30809232, 2019). "In contrast to previous reports of higher levels of IL-12, IFN-γ and lower IL-10 expressions in uncomplicated and SM, a lower level of IL-12 in uncomplicated malaria was observed which got further depressed in SM." (PMID 31614626, 2019). "The presence of anti-inflammatory cytokines, especially IL-10, suppresses parasite clearance, hindering the development of anti-parasite immunity, and clinical malaria, while promoting the development of asymptomatic infections." (PMID 31681289, 2019). "Malaria-induced inflammation leads to a compensatory secretion of the anti-inflammatory cytokine IL-10 and IL-10 can directly induce HO-1." (PMID 29980206, 2018). "Specifically, we would have expected higher levels of IL-10 in our group with uncomplicated malaria." (PMID 29555909, 2018). "The high levels of IL-10 during clinical malaria episodes accompanied with downregulated IFN-γ production observed in this study are likely to create a conducive host environment for the survival of P. falciparum." (PMID 30154871, 2018). "Patients infected with P. vivax or P. falciparum presented an increase in IFN‐γ, TNF‐α, IL‐6, IL‐8, IL‐10, IL‐13, MIP1β, and G‐CSF levels during the malaria acute phase." (PMID 29314720, 2018). "In humans, IFN-γ levels to schistosome egg and worm antigen has been found to decrease during pregnancy and high IL-10 levels as well as IFN-γ, TNF-α, IL-10 and IL-6 have been found to be associated with pregnancy associated malaria." (PMID 29970128, 2018). "Murine models of malaria demonstrate a regulation of balance between IL-10 and inflammatory cytokines such as IFN-γ and TNF-α." (PMID 29970128, 2018). "Prenatal exposure to P. falciparum significantly affects IFN-γ and IL-10 cytokine response during clinical malaria episodes in infants aged zero to two years." (PMID 30154871, 2018). "Since both IL-6 and IL-10 have been found to be up-regulated in ATBF and MSF as well as IL-10 in malaria, these results suggest common effects of R. felis and P. falciparum." (PMID 29736763, 2018). "It is well known that regulation of pro-inflammatory (IFN-γ, TNF-α, IL-6, IL-17) and anti-inflammatory (IL-10, IL-4) cytokines play a pivotal role in malaria parasite growth, protection, and/or pathogenesis." (PMID 29892278, 2018).
malaria (continued). "Geometric means of IL-10 in exposed and unexposed infants during clinical malaria episodes were 22.4 pg/ml (95% CI: 19.4-28.4) and 15.1 pg/ml (95% CI: 12.4-17.6), respectively, and the difference was statistically significant (P=0.01)." (PMID 30154871, 2018). "This study aimed at determining the effect of prenatal exposure to P. falciparum on Interleukin-10 and Interferon-γ responses during clinical malaria episodes in the first 24 months of life." (PMID 30154871, 2018). "Plasma levels of IL-10 in children with asymptomatic and mild malaria were found to correlate positively with the parasite load and to reduce significantly after the parasites in the peripheral blood were cleared." (PMID 29970128, 2018). "SNPs in the IL-10, CTL4 and TLR4 genes have been significantly associated with lower risk of clinical malaria, while a SNP in the IRF1 gene has displayed an enhanced risk." (PMID 28243235, 2017). "Additional cytokines were elevated in malaria cases compared to healthy controls and included IL-1ra, IL-10, IL-8/CXCL8, and macrophage inflammatory protein 1β (MIP-1β)/CCL4." (PMID 28775960, 2017). "In this study, we revealed that only the non-Vγ9 γδ T cells from people living in malaria-endemic areas proliferated and produced IL-10 in PBMC cultures stimulated with IL-2 and/or Pf Ag for 10 days." (PMID 28769886, 2017). "Our data suggest opposing roles for TNFα and IL10 Pf-specific CD4 T cells in naturally acquired immunity to malaria in children." (PMID 29097996, 2017). "IL-10 levels in all malaria groups were significantly (P < 0.001) lower in convalescence (medians, 4.13 pg/ml for UCM, 4.50 pg/ml for SMA, and 4.64 pg/ml for CM) than in acute disease." (PMID 28122790, 2017). "This is the first report demonstrating that, in UMPs living in a malaria-endemic area, a γδ T cell subset, the non-Vγ9 γδT cells, expands and produces IL-10." (PMID 28769886, 2017). "IL-10 is an anti-inflammatory factor that is critical for modulating inflammation in patients with severe malaria." (PMID 29312230, 2017). "IL-27 has been implicated in the induction of IL-10 production by Th1 cells in malaria and leishmaniasis; however, the role of IL-27 in regulating T cell production of IL-10 during M. tuberculosis infection is still unclear." (PMID 28584007, 2017). "Two inflammatory markers were useful as biomarkers for malaria in pregnancy: the cytokine IL-10 and soluble cytokine receptor sTNF-RII." (PMID 29255607, 2017). "The IL-10-to-TNF-α ratios for all three malaria types (medians, 2.10 for UCM, 2.60 for SMA, and 3.65 for CM) in convalescence were similar to ratios in controls (median, 1.63)." (PMID 28122790, 2017). "The plasma level of IL-10 was elevated in patients with high parasitaemia and with more than five previous malaria episodes." (PMID 28118834, 2017). "Severe malaria patients display increase levels of pro-inflammatory cytokines, TNF, IL-6 and IFN-γ while acute malaria individuals show high levels of the anti-inflammatory cytokines IL10." (PMID 28288644, 2017). "The response of anti-inflammatory cytokines such as IL-10 and IL-10/TNF-α, IL-10/IFN-γ and IL-10/IL-6 ratios in clinical malaria caused by P. vivax was short-lived and positively correlated with parasitemia rather than with the symptoms." (PMID 28243235, 2017). "In a small study, baseline regulatory cytokine gene expression (TGF-β and IL-10) at the time of vaccination with the malaria vaccines RTS,S/ASO2A and MVA-CS showed an inverse correlation with subsequent antibody responses." (PMID 28855899, 2017). "This agrees with previously published work demonstrating that cytokines, including IL-10 and IL-27, are important in BM responses during rodent malaria and/or in malaria patients." (PMID 28938907, 2017). "The levels of TNF, IL-6 and IL-10 also increased in the serum of the same three groups during blood stage Malaria." (PMID 27446022, 2016).
malaria (continued). "In the present study, data demonstrated that patients with P. vivax recurrent malaria presented an unbalanced CD4+/CD8+ T-cell ratio, which was associated with a significant increase in the plasmatic IL-10 levels." (PMID 27581163, 2016). "It was also noted an increased proportion of subjects with high plasmatic IL-10 levels, selectively in patients with recurrent malaria (p = 0.011)." (PMID 27581163, 2016). "IL-10 in response to EBNA1 was also produced within the CD4+ T cell Foxp3- populations in contrast to the malaria antigen, PfSEA-1 that only stimulated IL-10 from Foxp3+ Tregs." (PMID 28033393, 2016). "The unbalanced CD4+/CD8+ T-cells ratio, as well as increased IL-10 levels were correlated with the number of recurrent malaria episodes." (PMID 27581163, 2016). "The data analysis demonstrated that both malaria groups have significantly increased levels of IL-2, IL-4, IL-6, IL-10, TNF and IFN-γ as compared to the endemic controls." (PMID 27581163, 2016). "The immune response induced by recurrent malaria revealed significant changes in the main T-cells subsets and also in relevant cytokines, particularly IL-10." (PMID 27581163, 2016). "The role HO-1 plays in the pathogenesis of severe malaria in IL-10−/− mice infected with P. chabaudi has yet to be studied." (PMID 27557867, 2016). "We previously reported that recent malaria exposure can dampen subsequent P. falciparum-induced inflammation via a regulatory state mediated in part by the anti-inflammatory cytokine IL-10 produced by CD4+CD25+Foxp3- T cells that also produce IFNγ and TNF5." (PMID 27506615, 2016). "In malaria patients, the levels of IL-6 and IL-10 were increased expressively in relation to other cytokines, supporting what was noted in other studies on non-complicated malaria." (PMID 27581163, 2016). "Supporting these findings, the data presented here demonstrated that the levels of IL-10 were directly proportional to the number of malaria episodes." (PMID 27581163, 2016). "The anti-inflammatory cytokines, specifically IL-10, are known to play a key role in abrogating a robust initial proinflammatory response to malaria, as well as recovery from anemia." (PMID 27418744, 2016). "The cytokine IL-10 plays a central role in determining the outcome of many different infections, including malaria." (PMID 27630165, 2016). "We note that blood lactate correlates with plasma arginase activity, IL-10, and sCD163 in malaria, consistent with a role of lactate in M2 activation." (PMID 27385484, 2016). "In this study, the high production of IL-10 was remarkable in patients with recurrent malaria, being very low in patients with primary malaria." (PMID 27581163, 2016). "The results demonstrated a significant positive correlation between the CD4+/CD8+ T-cells (ratio) and plasmatic IL-10 levels (pg/mL) selectively in recurrent malaria patients." (PMID 27581163, 2016). "It is also possible that transitional B cells function in an immunoregulatory capacity, similar to IL-10 producing T cells, in the context of malaria." (PMID 26939776, 2016). "It is also required that further investigation should be undertaken to shed light on the association between the decreased CD4+/CD8+ T-cell ratio and the increased plasmatic IL-10 levels during recurrent malaria." (PMID 27581163, 2016). "The findings indicate a direct association between the CD4+/CD8+ T-cells ratio and plasmatic IL-10 cytokine levels, selectively in patients with recurrent malaria." (PMID 27581163, 2016). "We show that IL-10 produced by Tr1 cells protects against IFNγ-dependent, TNF-mediated tissue damage, but limited the control of parasites that cause malaria and VL." (PMID 26765224, 2016). "High ratios of TNFα and INFγ levels to IL10 or TGFβ levels have also been observed in other studies in patients with severe malaria." (PMID 27802341, 2016).